Y_RNA (Y RNA )
Gene: Miscellaneous RNA gene on chromosome 5 (132,993,099 to 132,993,200, reverse strand). Ensembl gene ENSG00000199677.
Homologues: Orthologues: chimpanzee Y_RNA (100% identical), macaque Y_RNA (92% identical). Paralogues in human: Y_RNA (92% identical), RNY3 (91% identical), Y_RNA (91% identical), Y_RNA (90% identical), Y_RNA (89% identical), RNY3P1 (88% identical), Y_RNA (88% identical), Y_RNA (87% identical), RNY3P13 (86% identical), RNY3P16 (86% identical), Y_RNA (86% identical), RNY3P14 (85% identical), and 97 more.